PITX1 (paired like homeodomain 1)
Diseases named in the same sentence as PITX1 in open-access papers (continued):
Sharing a sentence is not in itself a finding about the gene and the disease.
melanoma (continued). "Moreover, overexpression of miR-19b and a decrease in PITX1 at both the mRNA and protein levels were observed in many malignant melanoma cell lines and patient samples compared to normal melanocytes." (PMID 25643913, 2015). "It is therefore likely that reduction of PITX1 and overexpression of miR-19b not only play a role in the development of malignant melanoma, but may also play a role in various other types of cancers." (PMID 25643913, 2015). "Additionally, PITX1 expression was lower in metastatic tissue than in primary melanoma tissue." (PMID 34526609, 2021). "Moreover, our previous data demonstrated that PITX1 expression is also down-regulated in melanomas." (PMID 31404068, 2019). "Although downregulation of PITX1 was reported in various types of human cancer, including colon cancer cell lines, prostate and bladder tumors, lung, and gastric cancers, Barrett’s-adenocarcinoma, oral tumors and malignant melanoma, this report is the first to show a role for PITX1 in ESCC." (PMID 29137437, 2017). "PITX1 binds to the promoter region of SOX9, promoting its transcription and thus suppressing the growth and proliferation of melanoma by inhibiting SOX10 and SAMMSON." (PMID 37841446, 2023). "Overexpression of PITX1 and ZCCHC10 inhibited hTERT expression, thus suppressing melanoma proliferation." (PMID 37841446, 2023). "In primary melanoma tissue, we found a positive correlation between SOX9 and PITX1 expression in the TCGA data set." (PMID 34526609, 2021). "For other genes, such as SPP-1, GDF15 (putative oncogenes), PITX-1 and CST6 (putative TSG), the major shifts in gene expression appear to occur at distinct but different times during the thickening of the primary melanoma tumors." (PMID 18442402, 2008). "Another report revealed that both PITX1 and SOX9 expressions were reduced in melanoma." (PMID 37841446, 2023). "PITX1 overexpression facilitated SOX9 expression by binding to the RE1 (-592/-588) and RE3 (-520/-504) sites within the SOX9 promoter region, thereby inhibiting melanoma cell proliferation and promoting apoptosis." (PMID 37841446, 2023). "Additionally, induction of PITX1 strongly suppressed SOX10 expression and SAMMSON transcription, which act as oncogenic driver genes in melanoma, via up-regulation of SOX9." (PMID 34526609, 2021). "Intriguingly, increased SOX9 expression by PITX1 eventually leads to suppressive effects on cell proliferation and induction of apoptosis via downregulation of SOX10 and SAMMSON, which play an oncogenic role in melanoma." (PMID 34526609, 2021). "In addition, overexpression of both the PITX1 and ZCCHC10 genes showed significant suppression of hTERT transcription when compared to that of each gene in melanoma cell lines." (PMID 31404068, 2019). "Five of the melanoma cases were PITX1-positive (melanoma tissue sample number 1, 5, 6, 7, 8) and nine cases were PITX1-negative (melanoma tissue sample number 2, 3, 4, 9, 10, 11, 12, 13, 14)." (PMID 25643913, 2015). "Knockdown experiments revealed that suppression of PITX1 resulted in decreased SOX9 expression, whereas overexpression of PITX1 led to activated and increased SOX9 expression, inhibiting the growth and proliferation of melanoma by suppressing SOX10 and SAMMSON." (PMID 37841446, 2023). "Interestingly, PITX1 binds to the SOX9 promoter region as a positive regulatory transcription factor; PITX1 mRNA expression levels were positively correlated with SOX9 expression, and negatively correlated with SOX10 expression in melanoma tissues." (PMID 34526609, 2021). "PITX1 thereby plays a crucial role in regulating oncogenic signaling pathways, such as telomerase activity and SOX-SAMMSON transcription, suggesting that control of PITX1 may strongly contribute to a novel therapeutic strategy to target melanoma." (PMID 34526609, 2021). "It is therefore likely that a negative feedback relationship exists for the regulation of PITX1 and miR-19b via SOX10 expression in melanoma cells." (PMID 34526609, 2021).
Liebenberg syndrome (12 papers, 2014 to 2026). "This is what happens at the Pitx1 locus, where different SVs underlying the Liebenberg syndrome, a congenital malformation associated to a partial arm-to-leg transformation, are associated with variable morphological changes." (PMID 40634330, 2025). "In this work, we expand on the ectopic activation of the hindlimb-specific transcription factor Pitx1 by one of its own enhancers, Pen, in forelimb tissues that causes the Liebenberg syndrome." (PMID 40634330, 2025). "Ectopic expression of Pitx1 in forelimbs likely causes the arm-to-leg-like morphological abnormalities characteristic of human Liebenberg syndrome." (PMID 30499775, 2018). "Pathogenic variants in PITX1 are associated with a limited spectrum of rare disorders, including congenital talipes equinovarus with or without long bone anomalies and/or mirror-image polydactyly, and Liebenberg syndrome." (PMID 41744514, 2026). "The PITX1 abnormality is associated with many bone related diseases including congenital clubfoot, with or without deficiency of long bones and/or mirror-image polydactyly, and Liebenberg syndrome." (PMID 29743058, 2018). "Mutations in the Pitx1 gene or its surrounding regulatory regions are also associated with avian foot feathering and several human limb abnormalities, including polydactyly, Liebenberg syndrome, and familial clubfoot." (PMID 30499775, 2018). "Here the authors show that reducing enhancer-promoter distance at the Pitx1 locus increases proportion of Pitx1 forelimb expressing cells, worsening skeletal defects in Liebenberg syndrome." (PMID 40634330, 2025). "We characterized deletions in the vicinity of PITX1 in patients with Liebenberg syndrome." (PMID 25315429, 2014). "Changes in Pitx1-Pen distance and its associated variation in the proportion of cells ectopically expressing Pitx1, but not in Pitx1 transcription per allele, provide a mechanistic framework to account for the variation in Liebenberg syndrome severity among cases described so far." (PMID 40634330, 2025). "Mono-allelic mutations in PITX1 are associated with congenital clubfoot, with or without deficiency of long bones and/or mirror-image polydactyly in addition to Liebenberg syndrome, defined by the presence of carpal synostosis, dysplastic elbow joints, and brachydactyly." (PMID 34356068, 2021).
clubfoot (11 papers, 2016 to 2025). The most common congenital deformation of the foot, occurring in 1 of 1,000 live births. "Initially, genes associatedwith clubfoot (PITX1, TBX4, HOXA9, HOXD10, HOXD12,HOXD13, HOXA9, TPM1, TPM2, COL9A1, FLNB, CASP8,CASP10, UTX, CHD1, RIPPLY2, CAND2, WNT7) werescreened for potential variants." (PMID 38952703, 2024). "Our data proved that the idiopathic form of congenital clubfoot was rarely associated with mutations and CNVs on PITX1 and TBX4." (PMID 36360195, 2022). "TBX4, a direct target of PITX1, has been linked to the pathogenesis of clubfoot." (PMID 40746736, 2025). "Notably, haploinsufficiency causes these human syndromes, and clubfoot is partially penetrant in Pitx1+/- mice, collectively pointing to an exquisite sensitivity of limb morphology to levels of Pitx1 and Tbx5 gene products." (PMID 26977633, 2016). "It has been reported that the development of clubfoot involves various genes, such as PITX1, HOXD9, and TBX4, thereby emphasizing the intricate nature of genetic contributions to this condition." (PMID 38858754, 2024). "In a patient with isolated familial clubfoot, a microdeletion present in over three generations involving the PITX1 gene was identified." (PMID 36360195, 2022). "Our study aimed to evaluate the prevalence of pathogenic variants in PITX1 and TBX4 in Italian patients with idiopathic clubfoot." (PMID 36360195, 2022). "To identify the PITX1 and TBX4 mutations responsible for clubfoot, we sequenced all the coding regions and exon-intron boundaries of 162 patients’ samples." (PMID 36360195, 2022). "Recent findings propose the involvement of PITX1 in clubfoot pathogenesis." (PMID 40746736, 2025). "Although no major gene in clubfoot etiopathogenesis has been identified, variants in the genes PITX1 and TBX4 have been intensively studied, but without consistent results." (PMID 38929227, 2024). "Moreover, by copy number variation analysis in a patient with isolated familial clubfoot, a microdeletion of 241bp involving the PITX1 gene was identified." (PMID 36360195, 2022). "Several studies support the evidence of the crucial role of PITX1 (MIM 602149) and TBX4 (MIM 601719) genes in early limb development and clubfoot aetiology." (PMID 36360195, 2022).
lung carcinoma (11 papers, 2008 to 2025). "Strangely, another independent experimental study showed that PITX1 was reduced in lung cancer tissue compared to normal lung tissue." (PMID 37841446, 2023). "Hub genes including LRRK2, BMI1, MNDA (myeloid cell nuclear differentiation antigen), OTX1, FFAR2, and PITX1 play a significant role in lung cancer progression." (PMID 38137330, 2023). "An animal study has shown that high levels of PITX1 significantly increase the bone metastatic activity of lung cancer cells, stimulating increased osteoclast and proteolytic activity and promoting aggressive bone damage." (PMID 37841446, 2023). "Involvement of highly significant DEGs including SLCO1A2, OLFM4, RTKN2, CYP1A1, and MUC5AC plays a key role in rheumatoid arthritis development.Highly significant DEGs including OLFM4, RTKN2, CYP1A1, MUC5AC, CYP2A6, PCK1, and PITX1 have been reported to encourage the development of lung cancer." (PMID 38137330, 2023). "Moreover, high levels of methylation of the PITX1 promoter were found to be correlated with poorer overall survival in lung cancer patients." (PMID 37841446, 2023). "Besides, the abnormal PITX1 gene expression was also found in other pathological conditions such as lung cancer, cutaneous malignant melanoma and others." (PMID 29743058, 2018). "It is assumed that it functions as a tumor-suppressor gene in several human cancer types: decreased expression level of PITX1 is observed in various malignant tumors, e.g., HNSCC, gastric cancer, lung cancer, and colorectal carcinoma." (PMID 38540309, 2024). "PITX3 is a member of the PITX gene family, which includes PITX1, PITX2, and PITX3, all of which are related to lung cancer." (PMID 34631307, 2021). "PITX-1 has been identified as a TSG in several tumor types, including lung cancer and Barrett's esophagus leading to esophageal adenocarcinoma." (PMID 18442402, 2008). "PITX1 has also been found to be needed to inhibit RAS-induced tumorigenesis; in addition, several studies have shown that PITX1 expression is decreased in colorectal, prostate and lung cancer." (PMID 35456219, 2022).
colorectal cancer (10 papers, 2016 to 2025). A primary or metastatic malignant neoplasm that affects the colon or rectum. "A germline single nucleotide polymorphism in the PITX1 gene has been identified as a susceptibility locus for colorectal cancer." (PMID 29425237, 2018). "This study assessed the interaction between physical activity and colorectal cancer (CRC) risk based on a polymorphism in the paired-like homeodomain 1 (PITX1) gene in Koreans." (PMID 29484135, 2018). "Moreover, genome-wide association studies have identified single nucleotide polymorphism associated with susceptibility of colorectal cancer in East Asian patients, notably rs647161 (A/C) on 5q31.1, which matches the position of PITX1." (PMID 29425237, 2018). "In these, 8 SNPs were annotated to the same gene in pairs of height- and colorectal cancer risk-associated SNPs, leading to the following four gene annotations: BMP2, PITX1, DCBLD1, and BARX1." (PMID 28117334, 2017). "In colorectal carcinoma, PTP1B directly dephosphorylates PITX1 at Y160, Y175 and Y179, which destabilizes PITX1 and consequently results in downregulation of the PITX1/p120RasGAP axis." (PMID 34606417, 2021). "Sorafenib and regorafenib, both recognized as vascular endothelial growth factor receptor (VEGFR)-targeted drugs for advanced hepatocellular carcinoma (HCC) or colorectal cancer (CRC) patients, have exhibited the capacity to enhance the expression of PITX1 protein." (PMID 37841446, 2023).
colon cancer (8 papers, 2016 to 2025). "A significant interaction was observed between the physical activity based on MET-minutes per week and PITX1 genetic polymorphism in the risk of colon cancer among female." (PMID 29484135, 2018). "Further, the interaction between physical activity and PITX1 genetic variant in the risk of colon cancer was observed in female." (PMID 29484135, 2018). "In a large-scale sample test for colon cancer in East Asian populations (2098 cases in the experimental group and 5749 cases in the control group), PITX1 was identified as a new susceptibility gene that revealed a higher risk variant in East Asian populations than in European populations." (PMID 37841446, 2023). "However, a significant interaction was observed between regular exercise and PITX1 for colon cancer risk in entire subjects (p-interaction = 0.029)." (PMID 29484135, 2018). "Inhibition of PITX1 leads to activation of the RAS pathway and promotes tumorigenesis, whereas restoration of PITX1 in colon cancer cells suppresses tumorigenesis (Chapter 3 provides a detailed explanation of this phenomenon)." (PMID 37841446, 2023). "A study assessing the involvement of PITX1 in human cancer demonstrated that, PITX1 expression is reduced in gastric, bladder and colon cancers relative to that of normal tissues and concluded that PITX1 is likely a relevant tumor suppressor gene." (PMID 29484135, 2018). "The PITX1 genetic variant showed significant interactions with regular exercise and CRC risk (p-interaction = 0.018) and colon cancer risk (p-interaction = 0.029) among all subjects." (PMID 29484135, 2018). "The present study demonstrates a significant interaction between regular exercise, PITX1 rs647161 in the risk of CRC and colon cancer." (PMID 29484135, 2018). "A clinicopathologic study revealed that approximately 50% of colon cancer patients had reduced expression of PITX1, and a significant correlation was observed between the low expression of PITX1 and shorter prognosis, worse staging, and more positive lymph node metastasis in colon cancer patients." (PMID 37841446, 2023). "PITX1 has been reported to be involved in tumor formation in colon cancer." (PMID 37841446, 2023). "This suggests that PITX1 may act as a tumor suppressor gene and participate in the growth and metastasis of colon cancer." (PMID 37841446, 2023). "There was a significant interaction between physical activity and PITX1 genetic polymorphism in the risk of colon cancer among female (p interaction = 0.028) but not rectal cancer." (PMID 29484135, 2018). "In addition, PITX1 rs647161 genetic variant appeared to interact with regular exercise and CRC risk in all subjects and women in particular as well as with colon cancer risk among all subjects in the dominant model." (PMID 29484135, 2018).
gastric cancer (8 papers, 2017 to 2025). A primary or metastatic malignant neoplasm involving the stomach. "In contrast, PITX1 over-expression was associated with a more favorable outcome of osteosarcoma, colorectal, gastric cancer, and esophageal squamous cell carcinoma." (PMID 35267575, 2022). "In gastric cancer, PITX1 induces apoptosis and inhibits cell proliferation by binding to the apoptosis-related gene PDCD5 promoter and blocking the cell cycle in G1/S phase." (PMID 40342824, 2025). "The results showed that PITX1 was strongly or moderately expressed (100%) in the normal gastric mucosa, while 55 of 83 gastric cancer samples (66.3%) showed oppositely reduced the PITX1 expression." (PMID 37841446, 2023). "In gastric cancer, decreased expression of PITX1 can predict shorter overall survival; it is also known that PITX1 binds to the apoptosis-related target gene PDCD5 to suppress GC cell proliferation." (PMID 34868397, 2021). "PITX1 binds to the target gene PDCD5, which is an apoptosis related gene, so the down-regulation of PITX1 is associated with poor prognosis in gastric cancer." (PMID 32830857, 2020). "Additionally, another study found that overexpression of PITX1 increased the sensitivity of gastric cancer (GC) cells to 5-fluorouracil and cisplatin treatment, while silencing PITX1 promoted drug resistance in GC cells." (PMID 37841446, 2023). "Notably, PITX1 expression level was significantly negative correlated with gastric cancer differentiation, size, and infiltration depth (r = -0.316, P < 0.01)." (PMID 37841446, 2023). "Overexpression of PITX1 reversed the effects of miR-675 on EMT markers and positively regulated gastric cancer proliferation and invasion through the EMT and WNT/β-catenin signaling pathways, indicating that the miR-675/PITX1 axis may regulate GC invasiveness by modulating EMT." (PMID 37841446, 2023).
osteosarcoma (8 papers, 2019 to 2025). A usually aggressive malignant bone-forming mesenchymal neoplasm, predominantly affecting adolescents and young adults. "Our previous investigation demonstrated downregulation of PITX1 expression in osteosarcoma tissues was associated with poor survival of osteosarcoma patients." (PMID 40342824, 2025). "Conversely, it was reported that paired-like homeodomain transcription factor 1 (PITX1) packaged into exosomes released from osteosarcoma (OS) cancer cells mediates M2 macrophage polarization to promote OS metastasis via CCL22." (PMID 41294803, 2025). "For example, our laboratory previously found that PITX1 expression is down-regulated in osteosarcoma and correlates with patient survival and lung metastasis, and that PITX1 suppresses OS cell proliferation and metastasis by downregulating LINC00662." (PMID 40342824, 2025). "Paired-like homeodomain transcription factor 1 (PITX1) is frequently downregulated in cancers, including osteosarcoma (OS)." (PMID 36334221, 2023). "Moreover, heightened PITX1 expression correlated with improved outcomes in osteosarcoma, contributing to tumor inhibition via the modulation of Wnt/β-catenin, SMD, and Hippo signaling pathways." (PMID 37841446, 2023). "Elevated PITX1 inhibits osteosarcoma (OS) cell proliferation and migration." (PMID 37841446, 2023). "Their findings indicated significant upregulation of PITX1 in osteosarcoma, exhibiting a negative correlation with prognosis and lung metastasis." (PMID 37841446, 2023).
esophageal squamous cell carcinoma (7 papers, 2017 to 2024). Esophageal squamous cell carcinoma (ESCC) is a type of esophageal carcinoma (EC) that can affect any part of the esophagus, but is usually located in the upper or middle third. "DNA hypermethylation silences PITX1, and the hypermethylation of PITX1 is associated with poor prognosis in esophageal squamous cell carcinoma (ESCC)." (PMID 32830857, 2020). "Moreover, overexpression of PITX1 in esophageal squamous cell carcinoma cell lines significantly inhibited tumor growth in vivo." (PMID 37841446, 2023). "In esophageal squamous cell carcinoma (ESCC), PITX1 is expressed at low levels in tumors and is silenced by DNA hypermethylation." (PMID 34868397, 2021).